ROBO1 (roundabout guidance receptor 1)
Diseases named in the same sentence as ROBO1 in open-access papers (continued):
Sharing a sentence is not in itself a finding about the gene and the disease.
cancer (continued). "These subclones harbored putative metastasis-driving mutations in cancer-related genes such as SMAD4, ROBO1, and DICER1." (PMID 36476508, 2022). "In several studies, the Slit2/ROBO1 axis restrains the malignant phenotypes, such as migration, invasion and epithelial–mesenchymal transition, of cancer cells." (PMID 35236289, 2022). "Roundabout guidance receptor 1 (ROBO1), a cancer-promoting oncogene, has been negatively correlated with the prognosis of patients, due to ROBO1 promotes the genesis and progression of cancer metastasis." (PMID 35444536, 2022). "The endothelial-derived SLIT2 protein, together with its receptor ROBO1, drove cancer cells to migrate and infiltrate into endothelial tissue." (PMID 34007851, 2021). "ROBO1 acts like a natural inhibitor of metastasis; therefore, ROBO1 is considered as a potential cancer therapeutic target." (PMID 33540941, 2021). "We previously tried a photochemical internalization (PCI) method of a saporin-conjugated anti-Robo1 antibody for delivery into cancer cells and found a several hundred times augmentations of cytotoxic activity of anti-Robo1 IT." (PMID 32256588, 2020). "The epigenetic loss of TYW2 induces guanosine hypomodification in phenylalanine-tRNA, an increase in −1 ribosome frameshift events, and down-regulation of transcripts by mRNA decay, such as of the key cancer gene ROBO1." (PMID 32778592, 2020). "Further elucidation of mechanisms by which SLIT2/ROBO1 signaling simultaneously inhibits cancer cell migration and macropinocytosis will be important for potential development of new oncologic therapies." (PMID 32807784, 2020). "Robo1, an axon guidance receptor, has received considerable attention as a possible drug target in various cancers." (PMID 32256588, 2020). "SLIT2 (slit guidance ligand 2) and ROBO1 (roundabout guidance receptor 1) are a ligand and a cognate receptor, respectively, that trigger the signaling that controls axon guidance, neurogenesis and cancer progression." (PMID 31827074, 2019). "To investigate the role of Slit‐Robo family in GC, we first measured Slit2, 3 and Robo1, 2, 3 expression in 54 paired cancer tissues and matched adjacent non‐cancer tissues from GC patients." (PMID 30896071, 2019). "SLIT2/ROBO1 is a conserved ligand-receptor system that is involved in cancer cell proliferation, apoptosis, migration, and angiogenesis in a cell-type dependent manner." (PMID 29523788, 2018). "Taken together, the findings reveal a previously unappreciated function of SLIT2/ROBO1 signaling in OS, which is intertwined with metabolic alterations that promote cancer progression." (PMID 29523788, 2018). "Mechanistically, the SLIT2/ROBO1 axis exerted cancer-promoting effects on OS via activation of the SRC/ERK/c-MYC/PFKFB2 pathway." (PMID 29523788, 2018). "Cancer Cell Line Encycolopedia (CCLE) database was utilized exploring ROBO1 expression in cell lines." (PMID 28977866, 2017). "We checked Cancer Cell Line Encycolpedia (CCLE) database to explore ROBO1 expression level in mutiple HCC cell lines." (PMID 28977866, 2017). "The association of KAT2B with cancer progression/cell cycle was also shared by SGOL, ROBO1, and ICK, and represents the only functional overlap with genes identified with persistent and intermittent carriage of S. aureus." (PMID 26569114, 2015). "Anti-Robo1 monoclonal antibody has been reported to be an effective treatment for Robo1-expressing cancers." (PMID 20300657, 2010). "Specifically, the proximity and concentration of ROBO1-NK cells surrounding the organoids appear to confer a more focused and efficacious lysing effect, as opposed to the dispersed distribution observed with primary cancer cells." (PMID 39069888, 2024). "ROBO1 is a receptor known to be involved in the progression of cancer." (PMID 38790935, 2024). "ROBO1 is a receptor known to play a role in the progression of cancer." (PMID 38790935, 2024).
cancer (continued). "On the whole, these findings revealed the connections of CAFs and cancer cells through SLIT2/ROBO1 and inflammatory signaling, and the key molecules involved in this process may serve as potential biomarkers and therapeutic targets for GC." (PMID 37443302, 2023). "SLIT2, secreted by endothelial cells, acts as a chemoattractant for ROBO1-expressing cancer cells." (PMID 36942388, 2023). "Administering monoclonal antibodies (Mabs) against ROBO1 has shown anti-cancer potentials." (PMID 37238655, 2023). "However, ROBO1 was previously identified as a cancer suppressor gene, and growing has accumulated that Robo1 is specifically expressed in a wide range of malignant cells or neoangiogenic endothelial cells." (PMID 32256588, 2020). "The approach of our work paves the way to predict if mutations in ROBO1/4 and SLIT2 have the potential to disrupt their cognate physical interaction that in turn, could regulate the crucial hallmarks of cancer viz." (PMID 33318575, 2020). "Robo1 expression was significantly lower in GC tissues compared with matched non‐cancer tissues." (PMID 30896071, 2019). "Moreover, studies have shown that USP33-mediated SLIT2/ROBO1 signalling participates in the development of cancer." (PMID 29743814, 2018). "However, SLIT2/ROBO1 has also been correlated with poor prognosis and has reported cancer-promoting properties." (PMID 29523788, 2018). "Recent studies indicate that ROBO1 is closely related to cancer progression." (PMID 26610476, 2015). "ROBO1 is cleaved by MMPs and translocates into the nucleus of cancer cells, which suggests that ROBO1 may act beyond a receptor as a signaling molecule." (PMID 23593148, 2013). "In the present study, we found a new inhibitor of Robo1, miR-218, that may potentially be used to treat some types of cancer." (PMID 20300657, 2010). "Moreover, miR-588 exerted its cancer-suppressing effect by inhibiting ROBO1 expression." (PMID 36459288, 2023). "Previous studies have found several aberrations in ROBO1 that may be linked to the initiation and development of malignant tumors, although these variants have not yet been verified for causal implications." (PMID 35615148, 2022). "Although ROBO1 and GPC3 are often expressed in cytoplasm, there are also cases in which they are expressed on the cell membrane depending on the type of cancer." (PMID 40076777, 2025). "Representative examples of five common cancer antigens, GPC3, ROBO1, CLDN1, EphB4, and LAT1, expressed on the cell membrane of cancer cells are shown." (PMID 40076777, 2025). "Here, we have found roundabout guidance receptor 1 (ROBO1) was significantly upregulated in esophageal cancerous tissues and showed enhanced expression with the development of cancer staging." (PMID 40188129, 2025). "Three ongoing phase I/II trials are assessing ROBO-1-directed CAR-NK therapy in PDAC and other cancers." (PMID 40260240, 2025). "Over 20 trials are currently ongoing, recruiting, or under evaluation, targeting a diverse range of cancer-specific antigens such as Claudin6, NKG2D ligands, DLL3, and ROBO1." (PMID 40260240, 2025). "CLDN1, EphB4, LAT1, FOXM1, HSP105α, ROBO1, and SPARC were identified as potential targets for common cancer antigens for primary CRC." (PMID 40806530, 2025). "Conversely, blocking the interaction between SLIT2 and its receptor roundabout guidance receptor 1 (ROBO1) enhances the motility and invasiveness of PDAC cells, further supporting the inhibitory effects of SLIT2 on cancer cell migration and invasion." (PMID 39119085, 2024). "Its binding to roundabout guidance receptor 1 (ROBO1) can affect a variety of downstream pathways, such as β-catenin/LEF/TCF, PI3K/Akt, CXCL12/CXCR4 and RAFTK/Pyk2, and can regulate cancer invasion and metastasis." (PMID 37443302, 2023). "MALAT1 has been found to promote cell proliferation and migration of cancer cells by regulating the expression of genes promoting metastases, e.g., RASSF6, HNF4G, CA2, ROBO1, MIA2." (PMID 35887000, 2022).
cancer (continued). "They corresponded to cell fate determination, cell cycle activation, epigenetic modifications, DNA damage response, as well as cancer-related pathways including Wnt/β-catenin, PI3K/AKT/mTOR, Slit2/Robo1, MYC, and ErbB2-ErbB3 axes." (PMID 33747361, 2021). "In this way, MALAT1 influences proliferation, invasion and migration of cancer cells through regulation of multitudinous known downstream genes, including several metastasis-related genes (CCT4/CTHRC1/ROBO1/MIA2) and cell cycle control genes (p21/p27/B-MYB)." (PMID 31792655, 2020). "Some targets of miR-218, such as ROBO1, RICTOR, BIRC5 and LAMB3, have been reported to participate in many cancer signaling pathways, such as the ERK/MAPK, Wnt/β-catenin, and Notch pathways." (PMID 29717030, 2018). "USP33 deubiquitinates and thus maintains the stability of ROBO1, thereby regulating the activity of SLIT2 and inhibiting cancer cell metastasis." (PMID 29743814, 2018). "Axon guidance genes ROBO1 and ROBO2 are frequently lost in many cancers (head/neck, breast, lung, kidney and uterine cancers), and considered tumor suppressor genes (TSG) in them." (PMID 24272677, 2014). "We analyzed expression levels and intracellular localization of seven common cancer antigens, CLDN1, EphB4, LAT1, FOXM1, HSP105α, ROBO1, and SPARC, and human leukocyte antigen (HLA) class I via immunohistochemical staining of 85 surgical specimens from primaries and liver metastases." (PMID 40806530, 2025). "SLIT2 promoted the migration of endothelial cells and promoted the angiogenic activity via the ROBO1-VEGFR2-ERK1/2 signaling pathway; current data showed that the SLIT/ROBO pathway could be a promising therapeutic target for cancer." (PMID 36910471, 2023). "The kinase domain directly interacts with ROBO1, a process that is enhanced by SLIT2 stimulation, and it also increases the activities of inflammatory signaling and cytoskeleton remodeling, which is a key step in cancer metastasis." (PMID 37443302, 2023). "It is suggested that the saporin-conjugated anti-Robo1 immunotoxin comprises a novel therapeutic target in HNSCC by the application of saponin, and the drug delivery system developed here should prove to be applicable to other cancer targets." (PMID 32256588, 2020). "In conclusion, our data suggest that administration of 90Y-anti-ROBO1, which targets ROBO1, might become an effective tool for RIT treatment of HCC and can be applied to other ROBO1-positive cancers." (PMID 25006547, 2014). "The interaction between ROBO1 and SLIT proteins plays critical role in mediating axon guidance during neural development, recruitment of endothelial cells during angiogenesis, and cancer cell migration." (PMID 22860071, 2012). "It is very likely that SLIT2-ROBO1-ROBO4 might contribute to some of the variability associated with the differentiation status of HCC while expression of ROBO1 and SLIT2 also helps explain the stage differences in this cancer." (PMID 19114000, 2008). "Along with Robo1, other molecules like receptor protein tyrosine phosphatase alpha (RPTPα), myocyte enhancer factor 2D (MEF2D), and runt-related transcription factor 2 (RUNX2) are post-transcriptional target molecules of miR-218, which are known to induce cancer metastasis like MACC1." (PMID 27462788, 2016).
infection (5 papers, 2019 to 2025). The state of being infected such as from the introduction of a foreign agent such as serum, vaccine, antigenic substance or organism. "We detected genome-wide significant genetic associations with urinary bacterial relative abundances, in or near candidate genes including CXCL12, ABCC1, and ROBO1, which are implicated in urinary tract development and response to infection." (PMID 41364520, 2025). "In this manner, spatiotemporal regulation of SLIT2/ROBO1 activity may potently direct bacterial killing and confer effective host protection against pathogenic infection." (PMID 37773612, 2023). "The expression of miR-29-3p in HSCs began to decrease at 6 weeks post-infection, but the level of Robo1 mRNA was increased at this time." (PMID 37280619, 2023). "Genes affected by ROBO1 knockdown were mostly related to infection, inflammation, and immune response." (PMID 31194736, 2019). "In contrast, the expression level of Robo1 was significantly elevated at 8 weeks post-infection." (PMID 37280619, 2023). "Notably, we showed that miR-29a-3p targeted Robo1 in HSCs to prevent the activation of HSCs during infection." (PMID 37280619, 2023). "We further found that Robo1 expression in HSCs was significantly increased after infection." (PMID 37280619, 2023).
bacterial disease (2 papers, 2021 to 2023). "Together, these findings reveal that auto/paracrine SLIT2/ROBO1 signaling in HeLa cells impacts organelle control and innate immune defenses to bacterial infection via repression of mTORC1 under normal growth conditions." (PMID 37311584, 2023).
ROBO1 also shares sentences with these, for which no sentence is quoted: neurodevelopmental disorder (5 papers); Alzheimer disease (2); bipolar disorder (2); breast tumor (2); cardiovascular disease (2); colorectal (2); head and neck squamous cell carcinoma (2); neurodegenerative disease (2); oral cancer (2); Parkinson disease (2); proliferative retinopathies (2); renal cell carcinoma (2); renal fibrosis (2); squamous cell carcinoma (2); ventricular septal defect (2); acute pancreatitis (1); adenocarcinoma (1); adenomyosis (1); alcohol addiction (1); alcoholism (1); amyloid (1); aortic stenosis (1); Arrhythmia (1); ascending aortic aneurysm (1); autoimmune disease (1); autosomal dominant cerebellar ataxia (1); biliary tract cancer (1); Cerebral ischemia (1); cervical (1); childhood asthma (1).
A further 54 diseases each share a sentence with ROBO1 in 1 paper.